TMPRSS2 (transmembrane serine protease 2)
Diseases named in the same sentence as TMPRSS2 in open-access papers (continued):
Sharing a sentence is not in itself a finding about the gene and the disease.
SARS-CoV infection (continued). "Previous study suggested that camostat, a serine and cysteine protease inhibitor of TMPRSS2, can partially but significantly block SARS-CoV infection, and the combination with alostatin (a cathepsin inhibitor) could significantly enhance the antiviral effect of camostat." (PMID 35017320, 2022). "Although it was initially surprising that a scavenger receptor might be related to the response to coronavirus infection, a search of the related literature revealed that the scavenger receptor TMPRSS2 plays a critical role in SARS-CoV-2 infection as well as SARS-CoV infection." (PMID 34812273, 2021). "The transmembrane serine protease 2 (TMPRSS2) is crucial for cleaving IAV HAs containing monobasic cleavage sites and severe acute respiratory syndrome (SARS)-CoV-2 S in human airway cells." (PMID 39599912, 2024). "Transcriptomics revealed up-regulation of neurogenic and steroidogenic genes and down-regulation of DNA repair, cell cycle, circadian pathways and the severe acute respiratory syndrome (SARS)-CoV-2 host viral entry factors, ACE2 and TMPRSS2." (PMID 35328625, 2022). "During SARS-CoV infection, membrane-bound levels of active ACE2 can be decreased through TMPRSS2-mediated cleavage or by the infection itself." (PMID 36423166, 2022). "The expression of TMPRSS2 in three datasets, GSE33267, GSE47962, and GSE45042, was significantly reduced in response to SARS-CoV infection." (PMID 35017320, 2022). "Indeed, Matsuyama and colleagues showed that the localization of TMPRSS2-expressing cells in normal lung tissues, rather than ACE2-expressing cells, correlated to SARS-CoV infection in mild lesions, suggesting that TMPRSS2 may determine viral tropism at an early stage of SARS-CoV infection." (PMID 34239932, 2021). "In the present study, we aimed to explore the expression and prognostic power of ACE2 and TMPRSS2 in KIRC and KIRP, as well as the changes in ACE2 and TMPRSS2 in cells and an animal model with SARS-CoV infection, using a bioinformatics approach." (PMID 34131396, 2021). "The results indicate that SARS-CoV infection enhances the expression level of CTSB and TMPRSS2 genes after 1 day and 2.5 days, respectively." (PMID 34407143, 2021). "With HeLa cells expressing ACE2 and TMPRSS2, EST alone blocked ~34% of SARS-CoV infection, camostat mesylate blocked ~58%, and the two together blocked ~100% of the infections." (PMID 33290397, 2020). "Specifically, C57BL/6 mice, prone to a Th1-type immune response, and TMPRSS2 KO mice were used for SARS-CoV infection, while transgenic mice expressing the human DPP4 receptor for MERS-CoV (hDPP4-Tg) and hDPP4-Tg KO mice for TMPRSS2 were employed for MERS-CoV infection." (PMID 39858469, 2025). "Variation in expression of both TMPRSS2 and ACE2 suggests a credible hypothesis for correlation of vulnerability to SARS-CoV infection to age groups." (PMID 39086962, 2022). "TMPRSS2, human airway trypsin-like protease (HAT), TM protease, serine 13, serine protease DESC1, furin, factor Xa, and endosomal cathepsin L/B can cleave the SARS-CoV S-protein, facilitating SARS-CoV infection." (PMID 34122058, 2021). "In comparison, Tmprss2 mutant mice show no defects at baseline and are more resistant to the original SARS-CoV infection." (PMID 33164753, 2020). "In this study, TMPRSS2 knockout has resulted in downregulation of inflammatory cytokines and chemokine expression, which are involved in the bronchiolitis obliterans organizing pneumonia (BOOP), SARS, and pulmonary fibrosis in SARS-CoV infection." (PMID 33072093, 2020). "This is especially noteworthy in SARS-CoV infection where TMPRSS2 is not the sole mechanism for entry, as is the case with SARS-CoV-2." (PMID 32545518, 2020). "The Enrichr reported the SARS-CoV infection challenge at 60 hr (GSE47960) as the highly enriched sets from the GEO records of upregulated genes during virus perturbations, and also marked by the upregulation of TMPRSS2 expression in human airway epithelial cells." (PMID 34407143, 2021).
SARS-CoV infection (continued). "TMPRSS2 is especially an attractive target since it is not required for normal homeostasis; its inhibitor—camostat mesilate—is approved for human use in Japan for chronic pancreatitis, and camostat has been demonstrated to protect mice models from SARS-CoV infection." (PMID 33390974, 2020). "Also, other molecules required for SARS-CoV infection, such as TMPRSS2, might not be sufficiently expressed or function differently in bats." (PMID 32826334, 2020). "Additionally, we used the microarray GSE56677 and GSE52920 to illustrate changes in TMPRSS2 expression in vivo and in vitro after severe acute respiratory syndrome-coronavirus (SARS-COV) infection, finding that expression of TMPRSS2 decreased after SARS-COV infection in vitro." (PMID 33193689, 2020). "Other host proteases, such as transmembrane protease serine 2 (TMPRSS2) and airway trypsin-like protease TMPRSS11D, could also perform S1/S2 cleavage to activate the S protein for non-endosomal virus entry at the cell plasma membrane during HCoV-229E and SARS-CoV infection." (PMID 28933406, 2016).
prostate adenocarcinoma (39 papers, 2010 to 2025). "FISH may also identify a narrow deletion on 3p14 which is associated with TMPRSS2-ERG fusion characteristic only for prostatic adenocarcinomas." (PMID 22901743, 2012). "TMPRSS2:ERG gene fusion (T:E fusion) in prostate adenocarcinoma (PCa) puts ERG under androgen receptor–regulated (AR-regulated) TMPRSS2 expression." (PMID 41321318, 2025). "ERG is overexpressed in approximately half of prostatic adenocarcinomas as a result of a gene fusion with the androgen-driven promoter of the TMPRSS2 gene." (PMID 40141159, 2025). "TMPRSS2:ERG gene fusion negatively regulates PSMA expression in prostate adenocarcinoma (PCa) cell lines." (PMID 39083067, 2024). "TMPRSS2 showed most genetic alterations in prostate adenocarcinoma with alterations frequency of 4.81%." (PMID 36239108, 2022). "Similar to ACE-2, TMPRSS2 is over-expressed in prostate adenocarcinoma, lung and colorectal cancer, becoming an established tumour biomarker." (PMID 34399734, 2021). "Rearrangement of TMPRSS2–ERG in NEPC was a crucial finding to prove that NEPC is evolved from conventional prostate adenocarcinoma." (PMID 34956090, 2021). "The results showed that prostate adenocarcinoma patients with a high level of TMPRSS2 expression, and Gleason score exhibited a longer survival period." (PMID 33193689, 2020). "We demonstrate the scalability, efficiency, and utility of ProTECT on 326 samples from the TCGA Prostate Adenocarcinoma cohort, identifying recurrent potential neoepitopes from TMPRSS2-ERG fusions, and from SNVs in SPOP." (PMID 33244314, 2020). "The top 3 cancers with mutated ACE2 were undifferentiated stomach adenocarcinoma, esophageal squamous cell carcinoma and endometrial carcinoma and those with TMPRSS2 were prostate adenocarcinoma, undifferentiated stomach adenocarcinoma and melanoma." (PMID 33061814, 2020). "TMPRSS2-ERG is the most common fusion in prostate adenocarcinomas (50%) and in precursor high-grade prostatic intraepithelial neoplasia (approximately 20%), and promotes metastasis to bone." (PMID 31007851, 2019). "The frequency of these genes mutated in different cancers was no more than 10%, except TMPRSS2 in prostate adenocarcinoma with nearly 40%." (PMID 33061814, 2020). "TMPRSS2 has been shown to fuse to 20 different partners in prostate adenocarcinomas." (PMID 31007851, 2019). "Although expression of TMPRSS2-ERG or TMPRSS2-ETV1 fusion alone is insufficient to initiate prostate tumorigenesis, they appear to sensitize prostate epithelial cells for cooperation with additional oncogenic mutations to drive frank prostate adenocarcinoma." (PMID 25780911, 2015). "It has been reported that TMPRSS2 is overexpressed in tumors such as prostate adenocarcinoma (PRAD), and in contrast, the expression of TMPRSS2 is decreased in tumors such as head and neck cancer (HNSC)." (PMID 35281819, 2022). "In this study, we conducted the expression profiles of the TMPRSS2 gene for COVID‐19 in different normal tissues and PRAD (prostate adenocarcinoma) tumour tissues." (PMID 33609069, 2021). "The most recurrent example within any cancer type was TMPRSS2–ERG in prostate adenocarcinoma (PRAD; 38.2%)." (PMID 29617662, 2018).
prostate adenocarcinoma (continued). "In the present study, TMPRSS2-ERG gene fusion was identified through genomic testing, and the carcinosarcoma was confirmed to originate from prostate adenocarcinoma." (PMID 40969255, 2025). "For example, TMPRSS2-ERG gene fusion often predicts the progression and poor prognosis of prostate adenocarcinoma." (PMID 35547260, 2022). "Consistent with previous reports, the ERG, TMPRSS2, PTEN, and zinc finger protein family are closely related to the occurrence and progression of prostate adenocarcinoma." (PMID 35547260, 2022). "Approximately half of all prostate adenocarcinomas contain a fusion of an ETS transcription factor with a nearby gene, most typically ETS-related gene (ERG) with transmembrane protease serine-2 (TMPRSS2)." (PMID 25417144, 2014). "The fusion between the ETS-related gene ERG and the transmembrane protease, serine 2 (TMPRSS2), has been found in approximately 50% of the PSA-screened prostate adenocarcinomas." (PMID 23304520, 2012). "The TMPRSS2:ERG gene fusion (T:E fusion) puts ERG under the androgen receptor–regulated (AR-regulated) expression of TMPRSS2, and it is an early truncal alteration found in about half of prostate adenocarcinoma (PCa) cases in men of European ancestry." (PMID 41321318, 2025). "However, the expression of TMPRSS2 was lower in BRCA (breast invasive carcinoma), KICH (kidney chromophobe), LIHC (liver hepatocellular carcinoma), PRAD (prostate adenocarcinoma), STAD (stomach adenocarcinoma), and THCA (thyroid carcinoma)." (PMID 35558557, 2022). "We first asked whether, similar to TMPRSS2, ACE2 was also regulated by AR signaling in the human prostate adenocarcinoma cell line originally derived from a lymph node metastasis (LNCaP), which is AR expressing and androgen responsive." (PMID 34045511, 2021). "Thus, in this study, we performed the expression profile analyses of the TMPRSS2 gene for COVID‐19 in different normal tissues and PRAD (prostate adenocarcinoma) tumour tissues as a marker for targeted therapy." (PMID 33609069, 2021). "For each of the RNA-seq data sets corresponding to three adenocarcinoma and 3 non-tumour adjacent prostate tissue samples, we looked for the presence of a fusion gene, TMPRSS2:ERG, which is known to be common in prostate adenocarcinoma, and is a strong prognostic indicator." (PMID 21589938, 2011). "TMPRSS2 expression was upregulated in seven tumors, including cervical squamous cell carcinoma and endocervical adenocarcinoma (CESC), COAD, kidney chromophobe (KICH), prostate adenocarcinoma (PRAD), READ, uterine corpus endometrial carcinoma (UCEC) and uterine carcinosarcoma (UCS)." (PMID 34257580, 2021).
asthma (31 papers, 2020 to 2025). "Research focusing on the expression of ACE-2 and TMPRSS2 in the presence of IL-13 was conducted by collecting airway epithelial cells from patients with asthma via bronchoscopy." (PMID 40004141, 2025). "In asthma nasal epithelial cells, TMPRSS2 expression was increased, and ACE2 expression was decreased compared to that in the normal group." (PMID 36362417, 2022). "Among patients with asthma, male sex, African American race, and history of diabetes mellitus were associated with higher expression of ACE2 and TMPRSS2." (PMID 34261543, 2021). "Peters at al. confirmed that the use of ICS by those with asthma is dose-dependently associated with reduced ACE2 and TMPRSS2 gene expression, in contrast to systemic corticosteroids." (PMID 34742332, 2021). "Eventually, in the Severe Asthma Research Program cohort (SARP), sputum gene expression of ACE2 was found to be lower than TMPRSS2, but expression levels of both genes were similar in asthma and healthy controls." (PMID 34945846, 2021). "In patients with asthma, ICS use exhibited a dose-dependent association with reduced expressions of ACE2 and TMPRSS2." (PMID 33114246, 2020). "In the current study, LAM was the primary diagnosis in this patient cohort, however, some of these patients also had associated respiratory diseases, such as asthma, COPD, and pneumonia, which may have an add-on effect on ACE2, Furin and TMPRSS2 expression." (PMID 35160229, 2022). "These include ACE2 and TMPRSS2 in asthma patients as well as ACE2 and ADAM17 in COPD patients." (PMID 34081722, 2021). "With regard to asthma treatment, evidence suggests that ICS are associated with decreased ACE 2 and TMPRSS2 gene expression and that taking ICS may be beneficial in treating coronavirus infections." (PMID 33996694, 2021). "However, the gene expressions of ACE2 and transmembrane serine protease 2 (TMPRSS2) were similar in asthma and healthy controls in recent studies using samples from a severe asthma research program-3 (SARP-3) population." (PMID 34422204, 2021). "According to Severe Asthma Research Program-3 (SARP-3), the use of inhaled corticosteroids is linked with a decreased level of ACE2 and transmembrane protease serine 2 (TMPRSS2) gene expressions in asthmatic patients which are the key entrance receptors for SARS-CoV-2 infection." (PMID 34642587, 2021). "According to the Severe Asthma Research Program-3, inhaled corticosteroid treatment has been shown to decrease the number of ACE2 receptors and TMPRSS2 gene expression in sputum, both of which are associated with a reduced likelihood of SARS-CoV-2 entry through the airway." (PMID 34946251, 2021). "The dueling nature of increased TMPRSS2 but decreased ACE-2 expression may explain why asthma has not consistently been identified as a risk factor for severe COVID-19." (PMID 40004141, 2025). "TMPRSS2 exhibits high expression levels in human primary bronchial epithelial cells and the nasal lining and may be jointly regulated by airway inflammation and environmental factors, as it shows heightened expression in asthma and AR." (PMID 38204754, 2023). "The target receptor TMPRSS2 is modulated in response to air pollution and in autoimmune conditions such as asthma, which may affect the number of receptors available for SARS-CoV-2 to target, and ACE2 is involved in the renin-angiotensin system (RAS) which controls blood pressure." (PMID 33845766, 2021). "Understanding the expression of ACE2, TMPRSS2, and furin in the airways of people with asthma may help determine whether asthma itself or treatment with inhaled or oral corticosteroids may alter susceptibility to SARS-CoV-2 infection and potentially related disease severity." (PMID 32450087, 2020).
asthma (continued). "Furthermore, evidence has identified that IL-13 and other Th2 cytokines are key drivers of allergic inflammation and the patho-physiological changes in asthma, but may also be linked to reduced ACE-2 expression in asthmatic airway cells and an increase in transmembrane serine protease 2 (TMPRSS2)." (PMID 40004141, 2025). "Certain comorbidities such as asthma and diabetes mellitus lead to increased ACE2 and TMPRSS2 expression in lung cells." (PMID 35715729, 2022). "Rhinoviruses use ICAM-1 molecule (over-expressed within asthma patients with allergic airways), but SARS-CoV-2 uses angiotensin-converting enzyme 2 (ACE2) and transmembrane protease serine 2 (TMPRSS2) receptors." (PMID 35756853, 2022). "There are significant differences between the asthma cohorts that have been published so far that have looked at the expression of ACE2, TMPRSS2 and FURIN as compared to healthy controls." (PMID 33413387, 2021). "We also treated bronchial fibroblasts of severe asthma with IL-19 and assessed their ACE2 and TMPRSS2 expression." (PMID 35111161, 2021). "We hence determined whether ACE2 and TMPRSS2 are differentially expressed in the airway epithelium and lung tissue of large cohort of asthmatics (airway epithelium of SARP asthma cohort; GSE43696, and bronchial biopsies of U-BIOPRED cohort; GSE76227)." (PMID 35111161, 2021). "Interestingly, there was no apparent relationship of ACE2, TMPRSS2, or furin gene expression levels with asthma, cystic fibrosis or COPD status of native cells or ALI cultures." (PMID 35359837, 2022). "Although a differential expression of ACE2, but not TMPRSS2 was observed relative to age within the moderate and severe asthma groups, our data suggest that age may not be a key regulatory factor of its expression." (PMID 35111161, 2021). "However, asthma positive patients showed a significant reduction in TMPRSS2 mRNA expression compared with asthma negative patients (Student t-test p-value = 0.01)." (PMID 34357998, 2021). "Knowing the suggested ability of Type I and II cytokines to regulate ACE2 and TMPRSS2 expression, it was intriguing to understand how asthma-related cytokines and the type of lung tissue inflammation may regulate SARS-CoV-2 receptors in the different phenotypes of asthma." (PMID 35111161, 2021). "In general, ACE2, TMPRSS2, and furin gene expression in ALI cultures derived from COPD and asthma patients did not appear to be different in this limited set of samples." (PMID 35359837, 2022). "For example, studies in asthma patients showed elevated expression of ACE2, TMPRSS2, and FURIN in patients with severe but not mild-moderate asthma." (PMID 34262047, 2021).